MTOR (mechanistic target of rapamycin kinase)
Diseases named in the same sentence as MTOR in open-access papers (continued):
Sharing a sentence is not in itself a finding about the gene and the disease.
tumor (continued). "Key components of the PI3K signaling cascade are the p110á catalytic subunit (PIK3CA), the Phosphatase and Tensin homolog (PTEN) tumor suppressor, the downstream effector serine/threonine kinases (Akt), and the mammalian target of rapamycin (mTOR)." (PMID 22912864, 2012). "Immunohistochemistry of mTOR, p mTOR, and pS6K expression was performed to confirm that the increased expression was isolated to the tumor cells in mutant ovaries." (PMID 21695255, 2011). "Here, the effects of cucumin on carcinogenesis suppression were found to be mediated via inhibition of the AKT/mTOR pathway following analysis of treated and untreated tumor cell extracts." (PMID 21299897, 2011). "Mammalian target of rapamycin (mTOR) plays a critical role in tumor development, invasion, metastasis and angiogenesis that impact local recurrence and survival." (PMID 21513566, 2011). "Many preclinical experements suggest that the mTOR blockade has anti-tumor activity, displays radio- or chemo-sensitization, and overcomes the EGFR resistance." (PMID 21513566, 2011). "As the PI3K and mTOR pathways play a significant role in tumor angiogenesis, we examined the effects of NVP-BEZ235 treatment on microvessel density (MVD) through immunohistochemistry for the endothelial marker CD31." (PMID 21966435, 2011). "Expression of PI3K and mTOR is upregulated in aggressive RCC tumor cells, suggesting that these are valuable drug targets." (PMID 21834980, 2011). "We show here for the first time the phenotype of homozygous deletion of both Lkb1 and Pten in a given epithelium and demonstrate clear synergy in mTOR control in mouse urothelium, a synergy which normally leads to tumour suppression in this tissue." (PMID 21283818, 2011). "As inflammatory cells play a pivotal role in the tumor microenvironment, future studies will define the effect of mTOR inhibitors on inflammatory cells present in the tumor microenvironment." (PMID 24212820, 2011). "The mammalian target of rapamycin (mTOR) emerged as a critical pathway driving tumor growth by promoting the synthesis of new blood vessels and over-expression of proteins that control the progression of cell through the cell cycle, cyclins." (PMID 22758623, 2011). "Other dual PI3K/mTOR inhibitors have been evaluated and consistently showed the inhibition of tumor growth." (PMID 24212820, 2011). "The signalling components upstream and downstream of mTOR are frequently altered in a wide variety of human tumours." (PMID 21904669, 2011). "PI3K/Akt/mTOR inhibitors will sensitize the tumor vasculature to radiation both in vitro in cell lines and in vivo in xenogratfs." (PMID 21411864, 2011). "In fact, mTOR is an important mediator of tumor angiogenesis and the immunosuppressive effects of mTOR inhibitors has been known for decades and is being exploited in transplanted patients." (PMID 24212820, 2011). "In patient 2, constitutive activation of Akt and mTOR is similar to that in patient 1's recurrent tumor, and is seen in baseline pre-treatment tumor and in tumor that was resistant to IGF1R and mTOR combination treatment." (PMID 21494688, 2011). "The mTOR is considered a key signaling molecule that drives uncontrolled GBM tumor proliferation, and seems to be critical for breast CSC survival." (PMID 24212957, 2011). "The significant increase in CD133 expression in tumor cells from the first implantation after rapamycin treatment was similar to the effect of downregulation of mTOR in vitro." (PMID 22145042, 2011). "Constitutive activation of the PI3K/Akt/mTOR signaling axis leads to uncontrolled tumor cell proliferation and survival." (PMID 22039466, 2011). "A phase I clinical trial demonstrated that 63% of patients with PTEN-negative tumors displayed tumor regression when treated with drugs targeting the PI3K/Akt/mTOR signaling pathway." (PMID 22039466, 2011).
tumor (continued). "The overriding phenotype of these mice was of rapid onset of bladder EMT and neoplasia, both of which we show to be dependent upon MTOR activity." (PMID 21283818, 2011). "In in vivo and in vitro studies, mTOR inhibitor suppresses tumor growth and sensitizes HNSCC to radiation, cytotoxic agents and epidermoid growth factor receptor inhibitors." (PMID 21513566, 2011). "In this study, we have shown that activation of β-catenin and/or AKT increases mTOR activity and that inhibition of that activity with rapamycin suppresses the tumor burden by controlling cell proliferation and death." (PMID 21695255, 2011). "NVP-BEZ235 (Novartis) is a dual pan-class I PI3K and mTOR kinase inhibitor that has been demonstrated to reduce tumor growth in a number of different xenograft and several genetically engineered mouse (GEM) models and is currently in clinical trials." (PMID 21966435, 2011). "Tumor cell growth, proliferation, and apoptosis are regulated in part by a serine-threonine kinase called the mammalian target of rapamycin (mTOR)." (PMID 21672194, 2011). "The biologic activity of the mTOR inhibitor temsirolimus is further confirmed by the upregulation of nestin seen in the patient's IGFR/mTOR resistant tumor, since temsirolimus down-modulates EWS-FLI1, which would be expected to upregulate nestin." (PMID 21494688, 2011). "HDAC/mTOR inhibition in these RCC models also resulted in tumor apoptosis via greater inhibition of the anti-apoptotic, pro-angiogenic protein survivin." (PMID 22087262, 2011). "Lkb1 is a known tumor suppressor and a negative regulator of the mTOR/Insulin pathway, which has important roles in autophagy and nutrient sensing, while the Camptothecins function as DNA Topoisomerase 1 (Top1) inhibitors." (PMID 21909362, 2011). "High expression of phospho-P70S6 and AKT in the margin indicates that the activity of AKT/mTOR cascade is higher in tumor margin than in the tumor itself." (PMID 21513566, 2011). "mTOR inhibition suppressed tumor growth of EGFR-resistant cell lines and exerted an additive effect with the combination of the EGFR inhibitor." (PMID 21513566, 2011). "In vivo, perifosine and CCI-779 continued to show synergy in inhibiting the PI3K/mTOR axis corresponding with decreased tumor proliferation and induction of apoptosis." (PMID 21267448, 2011). "In support of these observations, it has been reported that the Akt-mTOR pathway is required for CNI-induced tumor growth." (PMID 21886838, 2011). "The administration of Rapamycin, an inhibitor of mTOR, decreased tumor size, proliferative rate, tumor multiplicity, and mTOR activity in NNK-treated mice." (PMID 21559252, 2011). "To assess the maintenance of CD133+ subpopulations in tumor cells in vivo by inhibition of mTOR, we injected LPC-H cells expressing mTOR-sh2 or control shRNA into nude mice." (PMID 22145042, 2011). "As a whole, these data suggest a possible use for mTOR inhibitors, either as a single agent to limit tumor growth and/or as an adjunct to radiation therapy." (PMID 21427787, 2011). "Others have shown that depletion of all three Akt isoforms promoted tumor regression through initiation of autophagy, and inhibition of mTOR with the alkylphospholipid perifosine induces autophagic cell death." (PMID 22039466, 2011). "Inhibition of mTOR induces apoptosis in some types of tumor cells, whereas they trigger autophagy in other settings." (PMID 20808909, 2010). "Salirasib is an S-prenyl-cysteine analog that has been shown to block ras and/or mTOR activation in several non hepatic tumor cell lines." (PMID 20860815, 2010). "A number of mechanisms can be at play to cause increased sensitivities of tumor cells to chemotherapy or radiotherapy, including inhibition of NF-κB, downregulation of transporters of the MDR family or the Akt-mTOR pathway." (PMID 20613989, 2010).
tumor (continued). "The anti-tumor activity of ridaforolimus, another intravenously administered mTOR inhibitor, has been evaluated in a phase II study of 52 patients with hematologic malignancies (including 9 patients with MCL)." (PMID 21092307, 2010). "Phospho-mTOR and p-p70s6K immunoreactivities were detected in 55 and 91% tumour specimens of all SCLC patients." (PMID 20683448, 2010). "The effect of treatment with AR and mTOR inhibitors was compared with the addition of an mTOR inhibitor to bicalutamide therapy, as tumours progressed on the anti-androgens." (PMID 20842117, 2010). "CP1's ability to interact with and protect TSC2 from inactivating phosphorylation by AKT retained TSC2 at the membrane, where it was active and able to exert its tumor suppressor function to repress mTOR." (PMID 20169078, 2010). "This study suggests that dual inhibition of AR and mTOR in castration-resistant xenograft models can restore sensitivity of tumours to anti-androgen therapy." (PMID 20842117, 2010). "These authors observed an unexpected significant down-expression of some Akt-regulated genes such as RPS6KB1 in their PIK3CA-mutated tumor series, but a normal level of AKT1 and mTOR transcripts." (PMID 21209903, 2010). "We observed here that the activation of the PI3K-Akt-mTOR pathway, whose aberrant function is one of the most frequent events in human neoplasia, represents an integral component of the normal cutaneous healing process." (PMID 20498714, 2010). "Rapamycin, as the first described mTOR inhibitor, has strong antiangiogenetic effects that inhibit tumour growth in numerous experimental models." (PMID 20459775, 2010). "In this model, the mTOR inhibitor RAD001 completely blocked both primary tumor growth and lung metastasis, and a MEK1/2 inhibitor (CI-1040) inhibited lung metastasis." (PMID 20146790, 2010). "Recent studies suggest a direct effect of VEGF-A on tumor cell proliferation the VEGFR2 via a mechanism thought to involve the AKT/mTOR pathway." (PMID 20072701, 2010). "We have previously shown that single agent IFN-γ, combination IFN-γ plus mTOR inhibitor, and combination sorafenib plus mTOR inhibitor are effective in the Tsc2-/- subcutaneous tumor model." (PMID 20146790, 2010). "We found that the activation of the PI3K-Akt-mTOR pathway, whose aberrant function is a frequent event in human neoplasia, represents an integral component of the normal wound healing process." (PMID 20498714, 2010). "The average mRNA expression levels of mTOR gene were significantly higher (0.23±0.16) in lung cancer than in adjacent-tumor tissue (0.12±0.09)(P < 0.01)." (PMID 20673489, 2010). "LS174T cells deficient for mTOR, raptor and rictor as well as LS174T expressing a scramble shRNA as a control were injected subcutaneously into nude mice and tumor growth was monitored." (PMID 20226010, 2010). "mTOR inhibition has been proven to result in reduced tumor cell growth and proliferation, decreased tumor angiogenesis and inhibition of cell metabolism." (PMID 21584218, 2010). "In order to evaluate optimal strategies for future clinical trials for TSC related tumors, we have reviewed all TSC tumor preclinical studies focusing on results that included positive findings with non-mTOR inhibitors." (PMID 20146790, 2010). "In summary, our studies show that interaction between the AR and mTOR pathways appears to be involved in tumour progression in the xenograft models." (PMID 20842117, 2010). "These two gene products form a tumor suppressor complex that functions to inhibit mTOR activity in a conserved cellular signaling pathway which is responsible for cell proliferation, protein synthesis, and nutrient uptake." (PMID 20146790, 2010). "Wortmannin and LY294002 are the best characterized PI3K inhibitors that have been widely used as research tools to elucidate the role of PI3K/Akt/mTOR signaling in various tumor cells." (PMID 20671809, 2010).
tumor (continued). "The mammalian target of rapamycin (mTOR) was intensively studied in a multitude of human tumour entities over the past couple of years." (PMID 20683448, 2010). "Predictors of response to inhibitors of the VEGFR-mTOR-HIF signaling axis are likely to be relevant to other tumor types in which these agents are active or in which mTOR/HIF signaling is critical." (PMID 20701793, 2010). "The preclinical data show that tumour regression after treatment with temsirolimus was limited to xenografts with high activation of the PI3K/Akt/mTOR pathway, as shown by high activation of p70S6K." (PMID 20664591, 2010). "The mammalian target of rapamycin (mTOR), which exists in two functionally distinct complexes, mTORC1 and mTORC2 plays an important role in tumor growth." (PMID 20226010, 2010). "Activated mTOR phosphorylates 4EBP-1 and p-p70s6K, which leads to protein translation and tumour growth." (PMID 20683448, 2010). "The threonine kinase mTOR is a key element of the intracellular signalling pathways involved in tumour cell proliferation, growth, survival and angiogenesis." (PMID 21045832, 2010). "Most data published with respect to tumour development in transplant recipients has been with the mTOR inhibitor, sirolimus." (PMID 20459775, 2010). "Pretreatment tumor biopsies were analyzed by immunofluorescence and laser scanning cytometry for the expression of pmTOR/mTOR, pAkt/Akt, pErk/Erk, pS6, p4EBP-1 and PTEN." (PMID 20630061, 2010). "It is well-established that upregulation of PI3K/Akt/mTOR signaling is important for conferring a growth advantage to tumor cells." (PMID 24281174, 2010). "Fluorescence in situ hybridisation analysis for mTOR and RPS6 loci showed that 11 of 33 and 21 of 44 tumours had loss of one copy of the respective genes, results which correlated with the loss of the relevant total proteins." (PMID 19401700, 2009). "Nuclear p-mTOR expression negatively correlated with the depth of tumour invasion, lymph node involvement, and the UICC stage (P<0.001,=0.035 and <0.001, respectively)." (PMID 19223902, 2009). "For the first time, this study shows that dose-dependent changes in tumour FDG uptake can be used to identify the OBD of an mTOR inhibitor in vivo." (PMID 19436299, 2009). "Mammalian target of rapamycin (mTOR) is a serine/threonine kinase involved in multiple intracellular signaling pathways promoting tumor growth." (PMID 19778445, 2009). "In previous studies the phosphorylation status of mTOR targets such as S6 protein from surrogate tissue or tumour samples has been commonly used as a marker of mTOR kinase activity and the degree of mTOR inhibition." (PMID 19436299, 2009). "mTOR was inhibited in tumor cells and normal airway epithelium, and steady state rapamycin levels were constant throughout the study." (PMID 19330036, 2009). "The pivotal role that mTOR plays in cellular signaling suggests a broad range of clinical utility, and indeed, phase I clinical evaluations of all 3 mTOR inhibitors provided preliminary evidence of anticancer activity in multiple tumor types." (PMID 19860903, 2009). "As such, the PI3K-Akt-mTOR pathway has been validated as a tumor therapeutic target of increasing interests." (PMID 19293927, 2009). "Immunostaining of phosp-S6K is significantly increased in tumor kidney tissue compared to normal kidney confirming the increase in mTOR activity." (PMID 19265534, 2009). "The immunosuppressive properties of mTOR inhibitors, coupled with their efficacy for tumor prevention in mouse models, suggested that modulation of the immune system is important for mutant K-Ras mediated lung tumorigenesis." (PMID 19330036, 2009). "Modeling activation of the PTEN/AKT/mTOR pathway in the Eμ-Myc mouse is a valuable tool to study tumor genotype/chemosensitivity relationships in vivo." (PMID 19412536, 2009). "In these mice, the mTOR inhibitor rapamycin appears to decrease both tumor cell proliferation and tumor size in a dose‐dependent fashion." (PMID 19076778, 2009).
tumor (continued). "TSC is caused by mutations in the TSC1 or TSC2 genes, whose products, hamartin and tuberin, form a tumor suppressor complex that regulates the PI3K/Akt/mTOR pathway." (PMID 19368729, 2009). "The use of mTOR inhibitors, either alone or in combination with other anticancer agents, has the potential to provide anticancer activity in numerous tumor types." (PMID 19860903, 2009). "Cytoplasmic p-mTOR expression positively correlated with the depth of tumour invasion (T1 vs T2–4, P=0.003), involved lymph nodes (P=0.010), and tumour stage (I vs II–IV, P=0.002)." (PMID 19223902, 2009). "We strongly suggest that these anti-VEGF treatments are suppressors of epithelial tumour cell growth factor acting as a surrogate AKT/mTOR signalling inhibitors on tumour cells." (PMID 19240722, 2009). "The cytoplasmic expression of p-mTOR positively correlated with the depth of tumour invasion (T1 vs T2–4; P=0.003), lymph node involvement (P=0.010), and UICC stage (I vs II–IV; P=0.002)." (PMID 19223902, 2009). "In tumours addicted to this growth factor stimulation, chemotherapy combined with mTOR inhibition has shown synergistic anti-tumour effects." (PMID 19127256, 2009). "Because S9 displayed potent inhibition on PI3K-Akt-mTOR pathway as well as tubulin polymerization, the ability of S9 to induce apoptosis was examined in various tumor cells." (PMID 19293927, 2009). "Mammalian target of rapamycin (mTOR) kinase is an important mediator of tumor cell growth and proliferation." (PMID 19159467, 2009). "Nearly all the tumours with nuclear p-mTOR or p-Akt expression showed cytoplasmic expression of the same molecule." (PMID 19223902, 2009). "S9 abrogated EGF-activated PI3K-Akt-mTOR signaling cascade and Akt translocation to cellular membrane in human tumor cells." (PMID 19293927, 2009). "This defined role for mTOR activity in the cellular processes that contribute to the development and progression of multiple tumor types has established mTOR as a major link in tumorigenesis." (PMID 19860903, 2009). "It is for these reasons that mTOR inhibitors are considered potential therapeutic agents in tumours where mTOR signalling is activated." (PMID 19401700, 2009). "In fact, inhibitors of PI3K-Akt-mTOR pathway have been manifested to sensitize tumor cells to apoptosis induced by cytotoxic drugs including DNA damaging agents and tubulin destabilizer." (PMID 19293927, 2009). "So far, only the effects of relatively high doses of mTOR inhibitors on tumour FDG uptake have been studied." (PMID 19436299, 2009). "Except for mTOR itself, many of the upstream and downstream components of the mTOR pathway are known to be either proto-oncogenes or tumor suppressors." (PMID 19521502, 2009). "Several tumour types that display sensitivity to paclitaxel also show activation of the PI3-kinase/Akt/mTOR signalling pathway." (PMID 19127256, 2009). "Cytoplasmic expression of p-mTOR was found in 69 (63%) of all tumours, and nuclear expression was found in 33 (30%)." (PMID 19223902, 2009). "As an inhibitor of PI3K-Akt-mTOR pathway, it is out of our expectation that S9 arrested tumor cells in M phase, which was attributed to its disturbance of microtubule cytoskeleton." (PMID 19293927, 2009). "Increased phosphoylation of S6Kinase at Thr389 in tumor kidney tissues indicated the increase in mTOR activity in tumor tissue." (PMID 19265534, 2009). "The two gene products form a tumor suppressor complex that regulates a conserved cellular signaling pathway (PI3K/Akt/mTOR) that mediates protein synthesis and cell proliferation." (PMID 19368729, 2009). "Phosphorylated Akt activates many downstream targets, including mTOR, and is thought to play a role in tumour progression." (PMID 19223902, 2009). "On the basis of our previous in vitro studies in MDA-MB-231 cells, we postulated that the inhibition of both EGFR and mTOR expressions would be important mechanisms for tumour suppression after combination treatment." (PMID 18797454, 2008).